MYCN (MYCN proto-oncogene, bHLH transcription factor)
Diseases named in the same sentence as MYCN in open-access papers (continued):
Sharing a sentence is not in itself a finding about the gene and the disease.
neuroblastoma (continued). "Within stage 4 neuroblastoma, correlation between MDM2 expression and poor event-free and overall survival is present in MYCN non-amplified tumors, but not in MYCN amplified tumors." (PMID 29416773, 2018). "In neuroblastoma tumors, the ESC mRNA signature score is significantly higher in tumors with versus without MYCN amplification (both in the global cohort and the subset of stage 4 tumors)." (PMID 30504901, 2018). "Conversely, only 17% (4 of 23) of the MYCN- non-amplified/favorable histology neuroblastomas showed focal or negative expression of PTEN, whereas 82% (14 of 17) of the ones with MYCN-amplified/unfavorable histology had this limited PTEN expression." (PMID 28881723, 2017). "MG-2477 treatment resulted in similar cell death induction and reduction of viability in all tested neuroblastoma cell lines, independent of the stage derived from, the PKB or the MYCN status." (PMID 28415610, 2017). "In the neuroblastoma cell lines there was no apparent relationship between the cell types (I, N, S) and their MEGF10 expression or methylation, nor between MYCN amplification and MEGF10 DNA methylation or expression." (PMID 27862318, 2017). "An examination of MYCN-amplified and non-amplified neuroblastoma cell lines revealed robust expression of GAS5 in both, but with no initial correlation to MYCN expression." (PMID 28035057, 2017). "To survey a broad range of aggressive neuroblastoma subtype backgrounds, we selected neuroblastoma cell lines either lacking (SK-N-AS, SH-SY5Y, SH-EP) or harboring (Kelly, IMR32, SK-N-BE) MYCN amplifications for in vitro analyses." (PMID 28036269, 2017). "Notably, TFAP4 did not regulate any genes in an antagonistic direction to MYCN in this subset of genes, suggesting that these two transcription factors cooperatively regulate specific target genes that play critical roles in the development of the aggressive phenotype of neuroblastoma." (PMID 27448979, 2016). "In contrast to the MYCN-amplified neuroblastoma cell line UKF-NB-3, SHEP cells do not harbor a MYCN amplification." (PMID 27517323, 2016). "To confirm the role of TFAP4 in neuroblastoma cell migration, we next performed cell migration assays after transiently overexpressing TFAP4 in MYCN non-amplified cell lines (SH-SY5Y and SK-N-FI), which express relatively low levels of both MYCN and TFAP4." (PMID 27448979, 2016). "We report here that N-Myc, an essential Myc family member, promotes conversion of glutamine to glutamate in MYCN-amplified neuroblastoma cells by directly activating GLS2, but not GLS1, transcription." (PMID 26528759, 2015). "All neuroblastoma cell lines used were HDAC8 positive, independent of MYCN oncogene amplification status." (PMID 25695609, 2015). "VMA and HVA levels were highly elevated, strongly pointing towards a neuroblastoma; a biopsy was made and showed a poorly differentiated neuroblastoma, intermediate MKI with unfavorable histology, and without MYCN amplification." (PMID 25077062, 2014). "Multivariate analysis of 106 primary neuroblastomas showed, as expected, that NCYM mRNA expression is not an independent prognostic factor from expression and amplification of MYCN." (PMID 24391509, 2014). "In contrast to primary tumors there was a trend of higher p110α levels in non-amplified neuroblastoma cell lines (SK-N-AS and SK-N-F1) compared to cell lines with 2p-gain (SH-SY-5Y and NB69) or MYCN amplification (SK-N-DZ and SK-N-BE)." (PMID 23597230, 2013). "Specifically in neuroblastoma tumors, low DKK3 expression correlated significantly with poor prognosis, however this was not independent of MYCN amplification." (PMID 23226679, 2012).
neuroblastoma (continued). "Because neither polySia-NCAM nor NCAM expression associated with MYCN amplification, which is a common feature in metastatic neuroblastoma, it appears that polySia-NCAM may be an independent marker for metastatic activity in neuroblastoma, like in rhabdomyosarcoma, NSCLC and SCLC." (PMID 19222860, 2009). "Compared to localized-non-amplified neuroblastomas, MYCN/c-MYC target gene expression gradually increases from stage 4s-non-amplified through stage 4-non-amplified to MYCN amplified tumors." (PMID 18851746, 2008). "Deletions of 11q have been noted in approximately 35% to 45% of neuroblastomas using microsatellite markers, CGH, and FISH and are consistently seen in MYCN non-amplified tumors." (PMID 17327916, 2007). "To broadly cover the phenotype of the tumor we used five neuroblastoma cell line including MYCN amplified (HTLA-230 and IMR-32) and not-MYCN amplified (SH-SY5Y)." (PMID 17760959, 2007). "It is conceivable that in neuroblastoma, MYC-driven transcriptional programs remain more intact or active, particularly in MYCN-negative cases, where C-MYC may act as a compensatory driver." (PMID 41614906, 2026). "Collectively, our work reveals a novel function of MYCN in transcription termination and suggests that the deregulation of MYCN and DDX17/DDX5 expression in neuroblastoma may lead to the expression of non-canonical and potentially harmful RNA molecules." (PMID 42209732, 2026). "The first is titled “Genomic profile of MYCN non-amplified neuroblastoma and potential for immunotherapeutic strategies in neuroblastoma”, showing that the fusion gene of CCDC32-CBX3 exists in 10 % of neuroblastoma patients." (PMID 39823827, 2025). "In view of MYCN/IGF2BP1 feedforward regulation, it was expected that IGF2BP1 alters sensitivity to BRDi and BTYNB (IGF2BP1i) synergizes with BRDi in non-MYCN-translocated neuroblastoma." (PMID 37246217, 2023). "We applied our in-house workflow; published ChIP-seq datasets obtained from studies in human neuroblastoma cell lines, which carried (COG-N-415, LA-N-5, and NB-1643) or lacked (NB-69) genomic amplifications of the MYCN as described, were subjected to rigorous bioinformatics processing." (PMID 37835497, 2023). "However, ZNF436 was a prognostic factor of neuroblastoma in E-MTAB-1781 dataset independent of age of diagnosis and MYCN amplification." (PMID 37904225, 2023). "Furthermore, 1p deletion was a prognostic factor of neuroblastoma in E-MTAB-1781, independent of MYCN amplification and age at diagnosis." (PMID 37904225, 2023). "To investigate the combined antimitotic/pro-apoptotic efficacy in established MYCN-driven neuroblastoma as a therapeutic option, we treated SHEP21N with the combination of antimitotic compounds and pro-apoptotic compounds at various dosages in a MYCN-negative and MYCN-induced setting." (PMID 37958555, 2023). "Upon activation with R848, a significantly increased secretion of IL6 was observed in the cocultures performed with the MYCN-nonamplified cell lines AS and SH, while IL6 secretion was enhanced after LPS activation in cocultures with the four neuroblastoma cell lines." (PMID 36923280, 2022). "In MYCN-nonamplified neuroblastoma, CCL2 produced by neuroblastoma cells induces the recruitment of antigen-presenting cells (DCs and monocytes/macrophages), allowing infiltration by T cells, in link with CCL19 and CCL22 production, hence favoring immune responses." (PMID 36923280, 2022).
neuroblastoma (continued). "Moreover, CCNE1 was a prognostic factor of paediatric neuroblastoma in the E-MTAB-161, E-MTAB-1781, E-MTAB-8248, GSE16476 and GSE49710 datasets, independent of MYCN amplification and age at diagnosis." (PMID 35655142, 2022). "Here, in this paper, we for the first time show that the iron chelator VLX600 inhibits mitochondrial respiration, decreases mTOR activity, reduces the expression of MYCN/LMO1 and induces an efficient cell death regardless of MYCN statues in neuroblastoma cells." (PMID 35805002, 2022). "Expanding on our prior observations in neuroblastoma, we noted appreciable differences in TIL enrichment pattern and expressional levels of immune checkpoints between MYCN-not amplified (MYCN.NA) and MYCN-amplified (MYCN.A) tumors." (PMID 34818552, 2021). "Directly downregulates MYCN and AURKA in neuroblastoma cells, which can potentially have a negative impact on their survival; miR-186 upregulation in NK cells resulted in the downregulation of TGFBR1 and TGFBR2 and, thus, impaired the TGFβ1-dependent inhibition of NK cells’ cytotoxicity." (PMID 33530529, 2021). "Therefore, we aimed to establish an isogenic model of such a deletion in the neuroblastoma cell line SKNSH, which is diploid with two intact copies of chromosome 11 and without MYCN amplification." (PMID 34230973, 2021). "Thus, rather than targeting N‐Myc directly, targeting downstream factors vital for N‐Myc's oncogenic effects is an attractive approach for the therapy of MYCN‐amplified neuroblastoma." (PMID 33497018, 2021). "Interestingly, these compounds exhibited similar potency in MYCN-amplified versus non-amplified neuroblastoma cell lines, which is consistent with a similar reduction of cell proliferation upon PRMT1 silencing regardless of MYCN amplification." (PMID 32415090, 2020). "Thus, as in retinoblastoma and neuroblastoma, high MDM2 was needed to maintain high-level MYCN but not MYC expression in SCLC cell lines." (PMID 33425720, 2020). "To further interrogate how MYCN and/or MYC protein(s) control CAMKV expression, we performed validation CHIP-sequencing for MYCN protein in the MYCN amplified neuroblastoma cell lines: COG-N-415, LA-N-5, NB-1643, and for MYC protein in the MYCN non-amplified lines: NB-69 and SK-N-SH." (PMID 32211329, 2020). "These experiments showed that this compound is particularly active in inhibiting in vitro growth of human neuroblastoma cell lines containing an amplification of the MYCN proto-oncogene (Kelly, IMR-32, LAN-1), while having only a limited effect on neuroblastoma cell lines lacking MYCN amplification." (PMID 33287862, 2020). "Here our RNA sequencing analysis identifies N-Myc, MYCNOS, IGF2BP1, lncNB1, RNF217, RP11-102F4.3, GRIK3, and SLCO5A1 as the RNAs most considerably over-expressed in MYCN-amplified, compared with MYCN-non-amplified, neuroblastoma cell lines." (PMID 31690716, 2019). "There was no correlative expression shown between MYCN and CTNNA2 in neuroblastoma cell lines." (PMID 31489113, 2019). "Therefore, restoring the expression of α-N-catenin can be a novel therapeutic approach for neuroblastoma patients who have the deletion of CTNNA2 and lack of MYCN amplification." (PMID 31489113, 2019). "In addition, they have the potential to be effective in a range of neuroblastoma genetic backgrounds, and unlike ATRA, are not restricted to MYCN amplified tumours." (PMID 31235824, 2019). "Titration experiments confirmed that MYCMI-6 discriminates between MYCN-amplified and MYCN-non-amplified neuroblastoma cell lines cells, with average growth inhibition of 50% (GI50) values of 2.5–6 μM for MYCN-amplified cell lines and around 20 μM or higher for MYCN-non-amplified cell lines." (PMID 29968736, 2018). "Within stage 4 neuroblastoma, correlation between MDM2 expression and unfavorable prognosis is limited to MYCN non-amplified tumors, indicating that the correlation is independent of MYCN status." (PMID 29416773, 2018).
neuroblastoma (continued). "We validated our protocols in a panel of 15 neuroblastoma cell lines and 2 MYC-amplified non-neuroblastoma cell lines to control for assay specificity, and reveal evidence for different MYCN or ALK status than previously reported for 7 cell lines commonly used in research." (PMID 29156716, 2017). "As a control, we also stably expressed the inactive GRD R1276P mutant (designated 'mut-GRD') into nf1a-/-;nf1b+/+;MYCN;EGFP fish, which led to a frequency of neuroblastoma at 12 weeks of age that was identical to that in fish not transgenic for either GRD construct (90.0%)." (PMID 27130733, 2016). "Thus, MYCN is a sufficient but not necessary regulator of CCNB1/cdk1 expression, and upregulaton of CCNB1 and cdk1 is a common feature of neuroblastoma cell lines irrespective of their MYCN status." (PMID 26029996, 2015). "Interestingly, GALNT14 higher expression significantly correlates with a worse OS in a public dataset of 88 NB samples (Tumor Neuroblastoma public - Versteeg - 88 - MAS5.0 - u133p2), either considering all NB patients or cases with no MYCN amplification, which alone has a strong impact on the OS." (PMID 26309160, 2015). "Here we report that low miR-497 expression levels are associated with event free survival (EFS) and overall survival (OS) in our neuroblastoma cohort and describe a significant difference in miR-497 expression between MYCN-amplified (MNA) versus non-MYCN-amplified (non-MNA) tumors." (PMID 23531080, 2013). "Since MYCN is a transcription factor, we considered whether or not MYCN could affect the expression of CD111 in neuroblastoma that would limit the clinical usefulness of M002." (PMID 24130898, 2013). "We treated a panel of neuroblastoma cell lines with a novel small molecule inhibitor of BET proteins, GSK1324726A (I-BET726), and observed potent growth inhibition and cytotoxicity in most cell lines irrespective of MYCN copy number or expression level." (PMID 24009722, 2013). "However, analysis of a previously published data set on MYCN binding sites in neuroblastoma cell lines indicated that MYCN does not bind to the PTPRD promoter region, revealing that down-regulation of PTPRD in MYCN amplified tumors is an indirect effect." (PMID 22305495, 2012). "Whether or not SKP2 is a direct target gene of MYCN, the prognostic significance of SKP2 overexpression in neuroblastoma has been demonstrated in primary tumor samples." (PMID 23226679, 2012). "However, transcriptional activity of MYCN or c-MYC as reflected by the transcript levels of direct MYCN/c-MYC target genes in relation to MYCN and c-MYC levels has not yet been defined in neuroblastoma subtypes." (PMID 18851746, 2008). "Notably, analysis of sequenced neuroblastoma patient samples, revealed a negative correlation between EPAS1 and MYCN expression and a strong positive correlation between EPAS1 expression, high expression levels of noradrenergic markers, and improved patient outcome." (PMID 41118218, 2025). "To assess whether TNFRSF4 expression was functionally relevant important for the oncogenic capacities of neuroblastoma cells, we carried out siRNA-mediated knockdown of TNFRSF4 in Kelly (MYCN amplified) and SK-N-AS (non-MYCN amplified) neuroblastoma cells grown in vitro." (PMID 38809883, 2024). "This suggests that DDX1 is sufficient to drive mTORC1 pathway activation in the context of MYCN amplification without affecting the oncogenic potential of neuroblastoma cells, which could generate the dependency on mTORC1 observed in cancer cells harboring DDX1-MYCN amplifications." (PMID 38197697, 2024). "Our data suggest that assessing STMN1 expression in neuroblastoma could be a powerful indicator of prognosis and that STMN1 might be a promising therapeutic candidate against refractory neuroblastoma with and without MYCN amplification." (PMID 37760452, 2023).
neuroblastoma (continued). "However, the SH-SY-5Y cells without MYCN amplification exhibited a higher sensitivity to BTZ because they were unable to upregulate HO-1, indicating the importance of NRF2 in targeting neuroblastoma chemoresistance and driving cell adaption to oxidative stress." (PMID 37835497, 2023). "Here, we showed that PARP and CHK1 inhibitors synergized to induce death in neuroblastoma cells and in primary cultures of SHH-dependent medulloblastoma, their combination being more effective in MYCN amplified and MYCN overexpressing cells compared to MYCN non-amplified cells." (PMID 34508175, 2021). "In this study, we focused on a subset of unfavorable neuroblastomas with a High-MKI and analyzed the pattern of MYC and MYCN protein expression compared to the distribution of conventional prognostic factors based on their MYCN oncogene status (amplified vs. non-amplified)." (PMID 29464082, 2018). "However, the high expression levels of cdk1/CCNB1 in cell lines with normal MYCN, which are also found in primary tumors in the absence of MYCN amplification, left us to conclude that MYCN is a sufficient but not a necessary driver of cdk1/CCNB1 in neuroblastoma cells." (PMID 26029996, 2015). "Therefore, to directly test whether neuroblastoma with low expression of MYCN could derive a biological advantage from α4 integrin expression, we established stable cell lines ectopically expressing integrin α4 with a c-terminal GFP-tag in the MYCNlow (NB5) NB cell line." (PMID 25973900, 2015). "However, using neuroblastoma cells that express more physiological levels of MYCN, we find that TRPM7 knockdown and overexpression do not affect proliferation in vitro, irrespective of MYCN amplification status." (PMID 25797249, 2015). "Importantly, while PRKCQ‐AS1 or MSI2 overexpression augments MYCN nonamplified neuroblastoma cell proliferation, MSI2 knockdown reverses PRKCQ‐AS1‐induced neuroblastoma cell proliferation, and PRKCQ‐AS1 knockdown blocks MSI2‐mediated neuroblastoma cell proliferation." (PMID 40103284, 2025). "However, as survival probabilities are equally poor for TMM positive and MYCN type and clearly separated from TMM negative, our study shows that DNA methylation-based classification can be used for diagnosing and subclassifying neuroblastoma into clinically relevant groups." (PMID 40713849, 2025).